BRCA1 (BRCA1 DNA repair associated)
Diseases named in the same sentence as BRCA1 in open-access papers (continued):
Sharing a sentence is not in itself a finding about the gene and the disease.
gallbladder cancer (5 papers, 2022 to 2025). "Although associations of BRCA1 PVs with colorectal and gallbladder cancers were observed, the results were not robust in the sensitivity analyses performed." (PMID 35077220, 2022).
gastric adenocarcinoma (5 papers, 2016 to 2024). "We also identified three gastric adenocarcinoma cases with significant BRCA1 promoter methylation." (PMID 38589664, 2024).
heart failure (5 papers, 2017 to 2025). Inability of the heart to pump blood at an adequate rate to meet tissue metabolic requirements. "Previous studies showed that some genetic alterations, including BRCA1, BRCA2, and ATM mutations, not only predispose to early-onset PCa but also correlate with increased cardiovascular risk and heart failure development." (PMID 40805117, 2025). "Of the 7.7% of BRCA1 and BRCA2 mutation carriers who developed heart failure, 8.3% were anthracycline naïve (statistically significant at p ≤ 0.001) compared with the general population risk of 2%." (PMID 28157161, 2017). "Interestingly, the regulon activity of BRCA1, a tumor-suppressor gene and potential regulator of heart failure, was also increased in FoamMac_2 and FoamMac_4 along cell fate B." (PMID 39766313, 2024). "One prior exploratory study of 401 patients, including 232 BRCA1 and 159 BRCA2 mutation carriers, showed an increased risk of heart failure based on self-reported symptoms elicited on an anonymous survey, relative to historical controls drawn from the general population." (PMID 35242827, 2022).
invasive lobular carcinoma (5 papers, 1996 to 2024). "Only one invasive lobular carcinoma was recorded and was categorized as BRCA1-associated." (PMID 32429297, 2020).
lung squamous cell carcinoma (5 papers, 2009 to 2024). "However, the Lung-MAP SWOG S1400G trial (NCT02154490) found that talazoparib (Talzenna) had a lower ORR of 4% in patients with advanced refractory lung squamous cell carcinoma, specifically in tumors with BRCA1/2, ATM, ATR, and PALB2 mutations." (PMID 38989152, 2024). "Somatic mutations of BRCA1 and BRCA2 were significantly associated with HRD in BRCA, OV, and BLCA, and lung squamous cell carcinoma (LUSC) (FDR < 0.002)." (PMID 34572800, 2021).
mastitis (5 papers, 2017 to 2025). Inflammation of breast tissue during lactation or postpartum due to an obstructed duct or infection. "The objective of our study was to analyse 89 missense SNPs belonging to six genes (CXCR2, CXCL8, TLR4, BRCA1, LTF, BOLA-DRB3), which were found to be associated with genetic resistance or susceptibility to mastitis." (PMID 37174521, 2023). "We have analysed the missense SNPs belonging to six genes (CXCR2, CXCL8, TLR4, BRCA1, LTF, BOLA-DRB3) and identified one marker (rs110124025) in BOLA-DRB3 that was associated with frequency of mastitis and with the number of affected quarters." (PMID 37174521, 2023). "Compared with GC-NPFFR2 rs109452259, which showed heterozygote advantage for SNF%, BRCA1 rs134817801 exhibited the opposite pattern, underscoring the diversity of non-additive effects among mastitis-associated loci." (PMID 41301948, 2025). "Proteins like complement C4 (C4), BRCA1, TLR4, MBLA, and calcium voltage-gated channel auxiliary subunit alpha2delta 1 (CACNA2D1) are reported potential biomarkers in mastitis which were also found in our study." (PMID 34222390, 2021). "Moreover, proteins like complement C4 (C4), BRCA1, TLR4, MBLA, and calcium voltage-gated channel auxiliary subunit alpha2delta 1 (CACNA2D1) have been found during mastitis in buffalo and are also reported as potential biomarkers in livestock mastitis." (PMID 39858163, 2025).
medullary breast carcinoma (5 papers, 2005 to 2019). An infiltrating breast carcinoma with a relatively favorable prognosis. "A total of 3 mutations in BRCA1 were identified among 14 (21.4%) women with a medullary breast carcinoma." (PMID 16168118, 2005). "We did, however, find three germline BRCA1 mutations in a set of 14 patients (21.4%) with medullary breast carcinoma selected for examination regardless of the family history." (PMID 16168118, 2005).
metastasis (5 papers, 2017 to 2024). The spread or migration of cancer cells from one part of the body (where they first appeared) to another. "Notably, BRCA1 mutation carriers and BRCA1/2 mutation carriers were significantly more likely to be positive in lymph node metastasis, when compared with non‐BRCA mutation carriers (p = 0.025 and 0.024, respectively)." (PMID 30972954, 2019). "Moreover, higher BRCA1-IRIS expression was associated with worse prognosis, and poorer outcomes after standard chemotherapy in Egyptian patients with TNBC, and lymph node and distant metastasis, and therefore higher AJCC stage." (PMID 28499366, 2017). "In a recent article, the overall rates of CNS metastasis were remarkably higher in patients with both BRCA1 and BRCA2 mutations than in noncarriers (BRCA1: 53% and BRCA2: 50% vs. noncarriers: 25%, respectively)." (PMID 33802424, 2021). "MMP16 expression is associated with age, tumor size, histology, clinical stages, lymph node metastasis status, PR status, HER2 status, non-TNBC, and BRCA1 status (P < 0.05), but not with other clinical pathological parameters." (PMID 39267845, 2024).
mismatch repair deficiency (5 papers, 2007 to 2025). "Two notable examples are the use of PARP inhibitors in BRCA1/2‐mutated cancers and immune checkpoint inhibitors in tumors with mismatch repair deficiency." (PMID 40847617, 2025). "The NCCN guidelines recommended olaparib and pembrolizumab for advanced PDAC patients with germline BRCA1/2 (gBRCA) mutations and mismatch repair deficiency (dMMR)/microsatellite instability (MSI), respectively." (PMID 36999792, 2023). "As an additional assessment of tumour characteristics, we conducted MSI analysis of tumours since the BRCA1 BRCT domain is known to bind to MLH1 and it has been suggested previously that mutations in the BRCA1 BRCT domain may cause mismatch repair deficiency." (PMID 18036263, 2007).
mucinous tumours (5 papers, 2008 to 2024). "Approximately 15% of index case women with a non-mucinous tumour have a mutation, and the mean age of presentation of a BRCA1-positive woman is 40 years." (PMID 38473013, 2024). "Some reports also noticed association of BRCA1 heterozygosity with non-mucinous tumor histology, high tumor grade, and improved survival." (PMID 19338682, 2009). "Two long-term BRCA2 survivors both diagnosed at aged 32 had mucinous tumours (the remaining histologies were high-grade serous: BRCA1=2, adenocarcinoma not otherwise specified BRCA1=5; endometrioid BRCA2=1), raising doubts as to whether these were HRD-driven tumours." (PMID 36894311, 2023).
ovarian carcinosarcoma (5 papers, 2017 to 2025). A highly aggressive malignant neoplasm arising from the ovary. "The one patient with a pathogenic mutation in BRCA1 had ovarian carcinosarcoma, a pathogenic mutation rate of 33% among ovarian carcinosarcoma patients tested." (PMID 37835384, 2023). "In this work, we identified a BRCA1/BRCA2 deleterious variant frequency of 50% (2/4) in ovarian carcinosarcomas." (PMID 32850417, 2020). "However, previous study showed that NU7441 could induce resistance to PARP inhibitor in BRCA1-defective cells, and BMS-754807 combined with carboplatin/paclitaxel was observed resistance in ovarian carcinosarcoma of patient-derived xenograft." (PMID 36685892, 2022).
pancreatic neuroendocrine tumor (5 papers, 2019 to 2025). Pancreatic endocrine tumor, also known as pancreatic neuroendocrine tumor (PNET), describes a group of endocrine tumors originating in the pancreas that are usually indolent and benign, but may have the potential to be malignant. "A cancer-associated variation (BRCA1 p.Lys1290fs) was detected in 1 of 119 patients with pancreatic neuroendocrine tumors (0.8%), and this patient was diagnosed at the age of 13 years." (PMID 35171259, 2022). "This letter to the editor reports subsequent rechallenge with peptide receptor radionuclide therapy (PRRT) in a patient with pancreatic neuroendocrine tumor bearing BRCA1 mutation previously treated with PRRT." (PMID 35403684, 2022).
Premature ovarian insufficiency (5 papers, 2020 to 2026). Amenorrhea due to loss of ovarian function before the age of 40. "The study showed that BRCA1 patients had a higher risk of premature ovarian insufficiency (POI) confirmed by a diminished ovarian reserve and a lower number of mature oocytes suitable for cryopreservation." (PMID 31872386, 2020). "Repair of such lesions depends on the Ataxia-telangiectasia mutated (ATM)–BRCA1 DNA repair-associated (BRCA1)/2 pathway, and impaired DNA repair accelerates follicular attrition, potentially precipitating premature ovarian insufficiency (POI, also termed premature ovarian failure)." (PMID 40867818, 2025). "Specifically, mutations in FANCM as well as FANCA, BRCA1/FANCS and BRCA2/FANCD1 are associated with premature ovarian insufficiency." (PMID 33500205, 2021). "Mutations in several DNA damage response and repair genes, including FANCM and BRCA1/2 as well as meiosis-specific homologous recombination genes (MSH5, RAD51), are implicated in primary ovarian insufficiency." (PMID 33500205, 2021). "Recent studies identifying factors responsible for primary and premature ovarian insufficiency (POI) have reported either dramatic downregulation or non-functional variants of several DDR pathway members, such as BRCA1, RAD51, ATR, MSH4, MSH5, and FANC genes." (PMID 40148269, 2025).
renal carcinoma (5 papers, 2009 to 2024). A carcinoma arising from the epithelium of the renal parenchyma or the renal pelvis. "However, BRCA1 mutation was less investigated in MA and other renal carcinomas." (PMID 30111351, 2018).
tauopathies (5 papers, 2019 to 2025). "Our results suggest that the coaggregation of BRCA1 and tau can occur in both three-repeat and four-repeat tauopathies and in both neurons and glial cells." (PMID 31861888, 2019). "We aimed to determine whether cytoplasmic accumulation of BRCA1 or its phosphorylated form, pBRCA1, is specific to cytoplasmic inclusions in tauopathies, or if it also occurs in α-synuclein-positive inclusions in Lewy body disease (LBD)." (PMID 39907307, 2025). "Sequestration of BRCA1 and 53BP1 in the cytoplasm by hyperphosphorylated and aggregated tau may therefore contribute to the progression of tauopathies." (PMID 33297375, 2020). "The aim of this study was to evaluate whether BRCA1 colocalizes with tau aggregates in the cytoplasm in human tauopathy patients’ brains." (PMID 31861888, 2019). "The aim of this study was to evaluate whether BRCA1 colocalizes with tau aggregates in the cytoplasm in the brains of the patients with tauopathy." (PMID 31861888, 2019). "However, whether colocalization and coaggregation of BRCA1 with tau also occurs in other human tauopathies had been unknown until recently." (PMID 31861888, 2019). "However, whether this dysfunction in BRCA1 also occurs in other tauopathies is unknown." (PMID 31861888, 2019).
tuberous sclerosis (5 papers, 2020 to 2025). Hereditary disease characterized by seizures, intellectual disability, developmental delay, and skin and ocular lesions. "Patients with heterozygous variants in BRCA1/2, tuberous sclerosis, and biallelic NBS-/-, as well as heterozygous ATM+/- mutations had similar low background rates." (PMID 41210219, 2025). "Patients with heterozygous variants in BRCA1 or BRCA2 and patients with tuberous sclerosis are comparable to oncology patients (p > 0.091) and are more sensitive to radiation than healthy individuals (p < 0.049)." (PMID 41210219, 2025).
undifferentiated carcinoma (5 papers, 2008 to 2022). A usually aggressive malignant epithelial neoplasm composed of atypical cells which do not display evidence of glandular, squamous, or transitional cell differentiation. "None of the endometrioid (n = 5), clear cell (n = 4), or low grade serous (n = 2) carcinomas showed loss of BRCA1, whereas 47% of the 38 high-grade serous or undifferentiated carcinomas had loss of BRCA1." (PMID 18208621, 2008). "Other histological types were also observed in BRCA1 carriers, the second most common being the endometrioid type, but there were also clear cell, adenocarcinomas, undifferentiated carcinoma and other types." (PMID 23536787, 2013).
urothelial carcinoma (5 papers, 2021 to 2024). A malignant neoplasm derived from the transitional epithelium of the urinary tract (urinary bladder, ureter, urethra, or renal pelvis). "They detected pathogenic variants of the BRCA1 gene in 2.3% and the BRCA2 gene in 2.1% in patients with urothelial carcinoma." (PMID 35395863, 2022). "Interestingly, targeted sequencing identified four mutations shared by all of the tissue samples, including the urothelial carcinoma: BRCA1 p.Val340GlyfsTer6, DICER1 p.Arg490His, IRS2 p.Arg744Cys, and PDGFRB p.Arg853Trp." (PMID 35260767, 2022).
uterine serous carcinoma (5 papers, 2004 to 2024). "We also review the evidence postulating on the possible inclusion of uterine serous carcinoma as part of the spectrum of malignancies seen in hereditary breast and ovarian carcinoma syndrome, driven by mutations in BRCA1/2." (PMID 26161390, 2015). "Until now, just a few reports were published linking BRCA1 and 2 mutations with uterine serous papillary carcinomas." (PMID 15083174, 2004). "Finally, BRCA1 was also shown to inhibit IGF1R expression in uterine serous carcinoma cells." (PMID 28706506, 2017).
chronic lymphocytic leukemia (4 papers, 2021 to 2024). "An increased risk of chronic lymphocytic leukemia has also been demonstrated in patients with mutations of either BRCA1 or BRCA2." (PMID 33954070, 2021). "A homozygous c.3082C > T (p.Arg1028Cys) BRCA1 mutation was reported in a patient, mother of two children, that developed a chronic lymphatic leukemia at 48 years without sign of FA or DNA damage hypersensitivity." (PMID 39596525, 2024).
clear cell renal cell carcinoma (4 papers, 2017 to 2024). "And there is a positive correlation between NBR1 and BRCA1 expression in clear cell renal cell carcinoma in supplementary (R = 0.355, p < 0.0001)." (PMID 29212269, 2017).
colorectal adenocarcinoma (4 papers, 2015 to 2024). The most common type of colorectal carcinoma. "Using two TCGA Colorectal Adenocarcinoma databases (Firehose Legacy and PanCancer Atlas) and the computational tool cBioPortal, we calculated the average age of CRC diagnosis in BRCA1 mRNA-low versus -high groups." (PMID 34611475, 2021).
colorectal tumor (4 papers, 1995 to 2025). "Whether BRCA1 inactivation is the carcinogenic driver of the colorectal tumor in that patient remains unresolved, and further studies are needed to determine its potential role as a CRC predisposing factor." (PMID 41194282, 2025). "A number of known or putative tumour-suppressor genes including NF1, BRCA1, NME1, NME2 and prohibitin are present on the long arm of chromosome 17, and this region has not been extensively analysed in colorectal tumours." (PMID 7734302, 1995).
endometrial tumor (4 papers, 2015 to 2021). "Tumor mutational signatures provided evidence that germline variation in BRCA1, PALB2, RAD51C, MUTYH and NTHL1 can be (but is not always) associated with tumor mutational signatures consistent with a functional role of these genes in endometrial tumor development." (PMID 33917078, 2021).
epithelial ovarian tumor (4 papers, 2009 to 2024). "In our previous study of BRCA1 and MIB-1 expression in ovarian epithelial tumors, we found that BRCA1 was highly correlated with MIB-1 expression in cystadenomas and borderline tumors." (PMID 28270171, 2017). "If we believe that ovarian epithelial tumorigenesis is a multi-step process, our finding that high correlation of BRCA1 and MIB-1 in OEIs supports the assumption that ovarian epithelial tumors at least some of them may arise from OEIs." (PMID 28270171, 2017).
germ cell tumor (4 papers, 2021 to 2025). A benign or malignant, gonadal or extragonadal neoplasm that originates from germ cells. "We showed differential response of germ cell tumor cell lines to Olaparib, associated with BRCA1/RAD51C promoter methylation." (PMID 33513287, 2021). "Although the data available today for the use of PARP inhibitors in advanced germ cell tumors are rather unpromising, these drugs could show a relevant therapeutic effect against the background of the existing BRCA1 variant." (PMID 40519304, 2025). "We present the case of a 47-year-old male with advanced non-seminomatous germ cell tumor, who was found to carry a heterozygous pathogenic BRCA1 germline variant following molecular testing due to a positive family history." (PMID 40519304, 2025).
Hyperglycemia (4 papers, 2020 to 2023). An increased concentration of glucose in the blood. "BRCA1 is another important tumor suppressor, and studies have shown that individuals with hyperglycemia had this gene naturally more methylated than normoglycemic individuals." (PMID 36046788, 2022). "In a similar experimental set-up, we investigated the influence of hyperglycemia on BRCA1." (PMID 31940810, 2020).
inflammatory breast carcinoma (4 papers, 2016 to 2025). An advanced, invasive breast adenocarcinoma characterized by the presence of distinct changes in the overlying skin. "In inflammatory breast cancer (IBC) models, PARP1 inhibitors achieve radiosensitization by delaying DNA double-strand break repair, an effect partially dependent on BRCA1 mutation status." (PMID 41367875, 2025).